HMGB1 (high mobility group box 1)
Diseases named in the same sentence as HMGB1 in open-access papers (continued):
Sharing a sentence is not in itself a finding about the gene and the disease.
epilepsy (continued). "The levels of HMGB1 are found to be higher in children who experience febrile seizures and subsequently develop epilepsy, compared to those who do not develop epilepsy." (PMID 40103702, 2025). "Interventional investigations on the IL-1β/IL-1R1/IL-1Ra and HMGB1/TLR4 pathways showed antiseizure effects, suggesting that these pathways could be therapeutic targets for epilepsy." (PMID 41155637, 2025). "It is suggested that HMGB1 and TLR4 expression levels correlate with epilepsy severity." (PMID 39046369, 2024). "Additionally, fisetin lowers the release of high-mobility group box 1 (HMGB1), reducing inflammation and neuronal damage in epilepsy." (PMID 39329119, 2024). "In the literature, the inflammatory pathway activated by HMGB1 in epilepsy does not use the RAGE receptor." (PMID 39046369, 2024). "Experimental and clinical studies suggest that the HMGB1/TLR4 pathway is involved in epileptogenesis induced by neuroimmune inflammatory responses and contributes to the neuroinflammatory response of brain injury after epilepsy." (PMID 39046369, 2024). "The role of HMGB1 is being investigated in the context of possible novel treatments targeting the DAMP in several neurological conditions, such as stroke, subarachnoid hemorrhage, traumatic brain injury, epilepsy and neurodegenerative diseases." (PMID 37048161, 2023). "The levels of HMGB1 and TLR4 increase in cerebral regions of patients with mesial temporal lobe epilepsy, focal cortical dysplasia type II (FCD-II) with epilepsy, or drug-refractory epilepsy, correlating with the severity of epilepsy." (PMID 38187384, 2023). "A growing body of research demonstrates that HMGB1 is generated from activated astrocytes and microglia, or neuron, subsequently interacts with the primary receptor TLR4 to involve in the pathophysiology of epilepsy." (PMID 38187384, 2023). "It is worth noting that the serum HMGB1 levels in children in the FS converted to epilepsy group were higher than that of children who did not convert to epilepsy (P < 0.05)." (PMID 36869074, 2023). "Through the process, anti-HMGB1 mAb reduces the TLR4 activity and other receptors that may involve in promote signal of epilepsy such as RAGE." (PMID 36310854, 2022). "It has been suggested that HMGB-1 and TLR4 expression levels correlate with epilepsy severity." (PMID 35837232, 2022). "In a study involving epilepsy by inducing upregulation of IL-1β and TNF-α mRNA was shown to be blocked by anti-HMGB1 through a potential anti-inflammatory mechanism that could inhibit microglia activation and proinflammatory cytokine synthesis." (PMID 36310854, 2022). "It has also been well established that HMGB1 plays a critical role in the pathogenesis of central nervous system (CNS) diseases, including ischemic brain infarction, ICH, traumatic brain injury (TBI), neuropathic pain, epilepsy, and Parkinson’s disease." (PMID 36230933, 2022). "Blocking of HMGB1 by regulatory axis using anti-HMGB1 mAb, reduced the TLR4 and others receptor that may involve in promote signal of epilepsy such as RAGE." (PMID 36310854, 2022). "We now provide evidence in primary human 3D cultures of constitutive antineurogenic signalling via the IL1-β-IL-1R and HMGB1 RAGE/TLR4 pathways and demonstrate pharmacological reversibility in tissue from patients with severe long-standing drug refectory epilepsy and memory impairments." (PMID 34548070, 2021). "Therefore, it is possible that the interaction of HMGB1 with TLR4 constitutes a potential link between ASD and epilepsy." (PMID 34198762, 2021). "In addition, we analyzed the expression (O.D. and positive stained area) of the TLR4 ligand HMGB1 in the hippocampus (CA1, CA3, dentate gyrus and hilus) and in the piriform lobe of dogs with epilepsy." (PMID 31959173, 2020).
epilepsy (continued). "Nevertheless, our findings offer a novel perspective representing HMGB1 a promising therapeutic target against epilepsy that not only suppress the epileptic seizure but also alleviate the seizure related memory impairment." (PMID 33732146, 2020). "HMGB1, as a common pathophysiological driver and prognostic biomarker after TBI, has the potential to constitute an innovative therapeutic target in several diseases such as neuroinflammation, epilepsy, and cognitive dysfunction." (PMID 33142949, 2020). "However, most of these previous studies investigating the function of HMGB1 and TLR4 in epilepsy were performed in experimental animal models or brain specimens; few clinical studies have been performed about the roles of HMGB1 and TLR4 in epilepsy patients." (PMID 31241711, 2019). "Furthermore, few studies investigated the effects of HMGB1 and TLR4 on drug resistance in patients with epilepsy." (PMID 31241711, 2019). "Moreover, accumulating evidence reported beneficial effects on evaluating anti-HMGB1 mAb and HMGB1 inhibitors against TBI, neuroinflammation, epilepsy, and cognitive decline." (PMID 30271319, 2018). "The plausible role of HMGB1 in epilepsy induced cognitive dysfunction has not yet been reported, though administration of anti-HMGB1 mAb in mice delayed epilepsy onset as well as ameliorated cognitive functions." (PMID 30271319, 2018). "Investigation on post-surgery patients with intractable epilepsy revealed increased levels of HMGB1, TLR4, RAGE, NF-κB, p65 and inducible nitric oxide synthase (iNOS) in the brain of the epilepsy group as well as increased levels of IL-1, IL-6, TNF-α, TGF-β, and IL-10 in epilepsy patients." (PMID 30271319, 2018). "TLR4 activation in neurons and astrocytes by HMGB1 proteins is a key mechanism of seizure generation and blocking TLR4 signaling using an antagonist could also reduce the severity of epilepsy." (PMID 30271319, 2018). "- Inhibiting the HMGB1/RAGE/TLR4 signaling axis could be a novel therapeutic strategy against several HMGB1 mediated conditions like TBI, neuroinflammation, epilepsy and cognitive dysfunction." (PMID 30271319, 2018). "Downstream of HMGB1, TLR4 mRNA expression is upregulated in response to brain insult, consistent with upregulation of this receptor during seizure activity in experimental models of epilepsy." (PMID 28086980, 2017). "Pharmacological interventions targeting HMGB1, TLR4, RAGE, and NF-κB may be effective for drug-resistant epilepsy in the future." (PMID 26485677, 2015). "We observed increased cytoplasmic translocation of HMGB1 IR in tumor tissue of patients with epilepsy compared to patients without epilepsy." (PMID 23270518, 2012). "Finally, children with FS who converted to epilepsy exhibited higher HMGB1 levels than those who did not convert to epilepsy (P<0.05)." (PMID 36869074, 2023). "Animal models of acute and chronic seizures have shown that HMGB-1 receptors are expressed after experimental seizures and HMGB-1/Toll-like receptor-4 (TLR4) signaling plays a role in generating and perpetuating seizures and might be targeted to attain anticonvulsant effects in epilepsies." (PMID 37583518, 2023). "Fortunately, recent studies show that anti-HMGB1 monoclonal antibodies (mAb) treatment might be effective in treating a wide range of central nervous system (CNS) and peripheral nervous system (PNS) disorders such as epilepsy." (PMID 36310854, 2022). "In this region, the HMGB1-positive area negatively correlated with age in control animals (Pearson correlation coefficient r = − 0.4529, p = 0.023), but not in patients with epilepsy." (PMID 31959173, 2020). "We hypothesized that the serum HMGB1 concentration would be elevated in dogs with epilepsy, regardless of the etiology." (PMID 33150666, 2020).
epilepsy (continued). "Although a pilot study in patients with focal DRE suggested that HMGB1 may be a candidate biomarker in epilepsy, HMGB1 is not specific to epileptic process; it’s presence has been associated with autoimmune and malignant diseases." (PMID 31156384, 2019). "Thus, either HMGB-1 blockage or TLR antagonist molecules would be able to reduce neuroinflammation and may be a novel target for developing anti-seizure drugs especially for drug-resistant epilepsies or anti-epileptogenic drugs." (PMID 37583518, 2023). "Hence, HMGB1/RAGE/TLR4 pathway may initiate the development and persistence of seizures in people and can be addressed to achieve anti-seizure results in drug-resistant epilepsies." (PMID 36310854, 2022). "Therefore, serum HMGB1 concentration could be interpreted to increase with the presence of epilepsy regardless of brain lesion volume." (PMID 33150666, 2020). "HMGB1 expression did neither correlate with neuronal density in control animals (CTRexp and CTRpat: Pearson correlation coefficient r = − 0.08606, p = 0.7426) nor in animals with epilepsy (Structural and Idiopathic: Pearson correlation coefficient r = 0.08736, p = 0.7766)." (PMID 31959173, 2020). "However, serum HMGB1 concentration of dogs with nonepileptic brain disease was not significantly increased, indicating that serum HMGB1 could be a biomarker of canine epilepsy." (PMID 33150666, 2020). "Thus, HMGB1/RAGE/TLR4 signaling might contribute toward the generation and perpetuation of seizures in humans and can be successfully targeted to attain anti-convulsant effects in epilepsies which are resistant to drugs." (PMID 30271319, 2018). "Analysis of HMGB1 staining intensity and labelled area in CA3 did not confirm relevant group differences when comparing animals with epilepsy with the control groups (F = 2.008, p = 0.1307)." (PMID 31959173, 2020).
colon carcinoma (101 papers, 2009 to 2025). "In a study, HMGB1-mediated RAGE activation was shown to reduce the accumulation of transcription factor Yes-associated protein-1 (Yap-1) in colon tumor cells in a RAS-dependent manner." (PMID 35296101, 2022). "Significantly elevated HMGB1 protein levels in colon cancer tissues are associated with poor prognosis and the absence of extensive macrophage infiltration." (PMID 36324584, 2022). "Positive correlation was found between HMGB1 protein expression in the nucleus and trophinin expression in tumor tissues, and its high expression in tumors of colon cancer patients is strongly linked to poor prognosis." (PMID 33117687, 2020). "High mobility group box 1 (HMGB1) secreted by tumor cells induced the suppression of DCs and is associated with lymph node metastasis in human colon cancer." (PMID 25254213, 2014). "The co-expression pattern of HMGB1 in colon cancer cells was inversely associated with the infiltration of both CD3+ and CD45RO+ T cells and 5-year survival rates." (PMID 20846416, 2010). "The results indicated that the co-expression of nuclear and cytoplasmic HMGB1 in colon cancer cells was associated with a poor prognosis." (PMID 20846416, 2010). "IHC in 20 clinical specimens of colon and rectal cancer also verified the expressions of HMGB1 and CTSL were higher in colon cancer than in paracancerous tissues, raising the necessity to determine the changes associated with HMGB1-mediated CTSL and autophagy-lysosome pathway." (PMID 37537587, 2023). "Furthermore, to understand the anti-cancer effects of C6 on the HMGB1-RAGE signaling pathway, the underlying mechanism of action of C6 was investigated in HMGB1-stimulated colon cancer HCT116 cells." (PMID 35408786, 2022). "Furthermore, HMGB1 expression was inversely associated with CD45RO+ T cell infiltration in colon cancer." (PMID 31399104, 2019). "However, only a few studies have shown the association between HMGB1 expression and 5-year survival in colon cancer patients." (PMID 20846416, 2010). "HMGB1 modulates the transcriptional activity in the nucleus, but it is also present in the cytoplasm and outside the cell in certain conditions, associated with the proliferation and metastasis of many tumors, including breast cancer, colon carcinoma, and melanoma." (PMID 20579387, 2010). "Ex vivo studies in MC38 colon cancer cell lines and hepatic metastasis models demonstrated that NETs promote release of high-mobility group box 1 (HMGB1), which activates Toll-like receptor 9 (TLR9) signalling in cancer cells." (PMID 41451221, 2025). "We observed HMGB1 overexpression and increased proliferative metaplasia (Ki67) in the hyperplastic mucosa (H) compared with mucosa distant from the colon cancer (C)." (PMID 38999957, 2024). "Following treatment with ICD inducers (oxaliplatin and mitoxantrone), miR-27a-3p knockdown induces more cell surface CALR and HMGB1 secretion by colon cancer cells compared to that observed in cells overexpressing miR-27a-3p." (PMID 39759512, 2024). "Here, we evaluate the clinical significance of polymorphisms in receptors for HMGB1, which is the hallmark of chemotherapy-induced immunogenic cell death, in patients with stage II–III colon carcinoma (COAD)." (PMID 37945630, 2023). "HMGB1 was strongly expressed in the nucleus of normal colonic epithelial cells, and this was reduced in colon cancer (p < 0.001)." (PMID 36980751, 2023). "On the other hand, overexpression of HMGB1 by an oHSV was shown to mildly increase the cytotoxicity of oHSV in hypoxic colon cancer cells in vitro." (PMID 36789106, 2023). "Our results suggest that five core genes, ELAVL1, GPX2, EPAS1, SLC7A5, and HMGB1, are involved in the ferroptosis of colon cancer cells." (PMID 36324584, 2022). "We identified five core genes, ELAVL1, GPX2, EPAS1, SLC7A5, and HMGB1, involved in the ferroptosis of colon cancer." (PMID 36324584, 2022).
colon carcinoma (continued). "As for HMGB1, it was found that shRNA and antisense oligonucleotides targeting HMGB1 gene can inhibit the proliferation and migration of colonic tumor cells." (PMID 35296101, 2022). "Another recent paper has reported that colon cancer exosomes containing HMGB1 can induce muscle atrophy via the TLR4/nuclear factor-κB (NF-κB) pathway and that serum levels of HMGB1 expression are upregulated in patients with colon cancer cachexia." (PMID 36497194, 2022). "The IHC score for HMGB1 in the normal and cancer cells of the colon cancer tissue in the CC group was higher than that in the control group." (PMID 33807620, 2021). "They found the expressions of c-IAP2 and HMGB1 were upregulated in 72.4% of colon cancer tissues, and that the expression of HMGB1 in tumor cell cytoplasm and nuclei was pronounced at tumor borders." (PMID 34267603, 2021). "In an immunohistochemical study, HMGB1 overexpression was determined as 55.6% in relation to tumour invasion, lymph node status, distant metastasis and stage of colon cancer disease." (PMID 34194625, 2021). "Previous studies have demonstrated that the expression and secretion of high mobility group box 1 (HMGB1) in mouse colon cancer cells, cutaneous squamous cell carcinoma (SCC) cells, LLC cells, and cervical cancer cells are significantly elevated following PDT." (PMID 32528867, 2020). "To identify the role of ERK1/2 in HMGB1-induced colon cancer cell proliferation, we performed western blotting and CCK8 assays using the ERK1/2-specific inhibitor U0126 in CT26 colon cancer cells." (PMID 33160389, 2020). "Taken together, our findings reveal a novel mechanism of HMGB1 in inflammation, providing therapeutic strategies for colon cancer." (PMID 32514250, 2020). "In HMGB1, Ser35, 39, 42, and 46 in NLS1, 181 in NLS2, and 53 close to NLS1 have been shown to be phosphorylated in macrophages after TNF-α and okadaic acid treatment, while Ser39, 53, and 182 of HMGB1 are phosphorylated by PKC-ζ in colon cancer cells." (PMID 32587593, 2020). "Since NF-kB as mediator effect on inflammatory response, above results further demonstrated that HMGB1 mediates LPS-induced inflammation in colon cancer cells." (PMID 32514250, 2020). "TCTP level in colon tumor tissues and HMGB1 level in serum of CRC patients were significantly increased." (PMID 33117687, 2020). "Increased plasma or serum levels of HMGB1 have been found in several cancers and higher circulating HMGB1 is associated with worse clinical outcomes in patients with CLL, colon carcinoma, or hepatocellular carcinoma." (PMID 30988279, 2019). "Acetylation and phosphorylation of HMGB1 lead to the translocation of HMGB1 from the cytoplasm and enhance the induction of HMGB1 secretion in macrophages and colon cancer cells." (PMID 29636841, 2018). "The results of this analysis showed that HMGB1 was passively released from the indicated colon cancer cell lines by HPA3P." (PMID 29487701, 2018). "Our work shows that the microenvironmental condition of glucose deprivation is responsible for the active release of HMGB1 from HT-29 colon cancer cells and other cancer cell lines." (PMID 26979829, 2016). "The results from western blot data showed that glucose deprivation triggered the release of HMGB1 from HT-29 colon cancer cells." (PMID 26979829, 2016). "In a more recent study we isolated HMGB1 from the cytotoxic granules of NK cells and tested its cytotoxic potential against colon cancer cells." (PMID 27652323, 2016). "The results suggested that, like the response of the HT-29 colon cancer cell line, glucose deprivation also triggered the release of HMGB1 from MCF-7 and A549 cells." (PMID 26979829, 2016). "Our results showed that the treatment induced both CRT expression in the plasma membrane fraction and HMGB1 expression in the total cell lysates, not only in mouse colon cancer cells but also in human colon cancer cells." (PMID 27363018, 2016).